CCND1 (cyclin D1)
Diseases named in the same sentence as CCND1 in open-access papers (continued):
Sharing a sentence is not in itself a finding about the gene and the disease.
tumor (continued). "Examining mice at 3-5 months of age, we observed an obvious border between the malignant and pre-malignant parts of the pineal gland [left]; this border disappeared as the tumor infiltrated the whole pineal gland [right], and SAHF were lost in the emerging Irbp-Cyclin D1, p18Ink4c -/- tumor." (PMID 22548705, 2012). "In addition, involvement of furin in repression of tumor growth was also supported by decreased expression of cell proliferation related molecules (IR, cyclin D1, CDK2, and CDK4...etc)." (PMID 22808247, 2012). "Other tumor markers that play an important role in lung carcinogenesis and are implicated in the treatment response of NSCLC patients should also be evaluated, namely cyclin D1, kRAS and EGFR (epidermal growth factor receptor)." (PMID 22701665, 2012). "Amplification of CCND1 was observed in 8.7% of the tumours, which is slightly lower than the frequency of 10 to 15% generally reported, even though some groups have demonstrated a lower percentage of CCND1-amplified tumours." (PMID 22475046, 2012). "Indeed, cyclin D1 was activated in lung tumors of both C57BL/6 and NOD/SCID mice and cyclin D1 is frequently overexpressed in NSCLC tumours and pre-invasive bronchial lesions." (PMID 23251519, 2012). "The ability of BLU to regulate transcription is speculated to influence the level of proliferation regulators, and engagement of signaling pathways involving JNK and cyclin D1 may mechanistically elucidate the tumor suppressive role played by BLU." (PMID 22727408, 2012). "The present study revealed that JNK and cyclin D1 are targets of tumor suppression exerted by BLU." (PMID 22727408, 2012). "Therefore, strategies to down-regulate cyclin D1 expression were reported to inhibit tumor angiogenesis in vitro and in vivo." (PMID 22359572, 2012). "Additionally, POU5F1, LGR5 and CCND1 were analysed, and tumour samples of patients with TRG2 or TRG3 (each n = 22) were studied." (PMID 22970250, 2012). "Also for intracellular antigens such as cyclin D1, successful detection of tumor cells has been shown in >90% of cases with blood involvement." (PMID 22738398, 2012). "Cyclin D1 is the target with the second most interesting preclinical data with cell line work in only a single cell line but further investigations included a mouse model showing that cyclin D1 seems necessary for tumor formation." (PMID 22988546, 2012). "However, we did observe decreased levels of total Cyclin D1 in OVCAR-4 tumor cells treated with OGT siRNA and 4 μM GDC-0941, relative to GDC-0941- or OGT siRNA-alone treated cells." (PMID 23029544, 2012). "In agreement with this, nuclear β-catenin levels increased and a number of its target genes including cyclin D1, Zeb1 and vimentin, also known for their role in tumor proliferation and invasion, were induced upon exposure of naïve cells to CM from their senescent counterparts." (PMID 23272224, 2012). "This was further validated by CHOP with 80% cyclin D1 expression of 25 ATRT primary tumor samples." (PMID 22988546, 2012). "In this scenario CDKN2A loss is coupled to tumor progression rather than initiation, perhaps by further promoting a CCND1 driven activation of the cell cycle G1 phase of the cell cycle." (PMID 22685613, 2012).
tumor (continued). "Surprisingly, however an inverse correlation between TN tumours and cyclin D1 levels was found." (PMID 24213463, 2012). "However, SCF has different F-box substrate recognition modules for both tumor suppressors, such as p27, p57, and p21 and oncogenes, such as Cyclin D1, mTOR, and c-Myc." (PMID 23029392, 2012). "Adding a Smo inhibitor to a regimen that targets cyclin D1 for repression might enhance clinical anti-tumor activity." (PMID 22923130, 2012). "To determine whether metformin affected cyclin D1 protein levels and apoptosis of tumor cells in vivo, we further analyzed cyclin D1 expression and apoptotic tumor cells in xenograft tumors by IHC and TUNEL staining, respectively." (PMID 23151022, 2012). "Thus, should ER-positive tumours that have lost expression of cyclin D1 be considered more ER-negative-like?" (PMID 21955753, 2011). "ER-positive tumours however are typically cyclin D1 high, thus by choosing tumours that are cyclin D1 low in this subgroup, we are more correctly mimicking our in vitro setting, where expression of cyclin D1 may have been lost." (PMID 21955753, 2011). "Given the poor outcome associated with metaplastic cancer, it may indicate why high ID1 expression in CCND1 low tumours gave the shortest RFS." (PMID 21955753, 2011). "To test if the nuclear clearing observed in PTCs could alter the immunoreactivity of the nuclear compartment in these specific tumours, we analyzed the expression of Cyclin D1 by using IHC." (PMID 21698151, 2011). "Further, relatively higher frequency of cyclin D1 immunoreactivity was also seen in patients with less differentiated tumours suggesting inverse correlation of cyclin D1 expression with histological differentiation of tumour." (PMID 21537087, 2011). "However, when examining ID1 high tumours, both the highest and lowest expression quartiles of CCND1 were correlated to reduced RFS/DFS but only in the ER-positive subgroup." (PMID 21955753, 2011). "Thirty-nine of 47 (82.97%) tumor tissue specimens were positive for cyclin D1." (PMID 22024187, 2011). "Whilst this may appear contrasting to our in vitro data, we reason that cyclin D1 low, ER-positive tumours best represent our cell line model." (PMID 21955753, 2011). "Erk1/2 inhibitor pretreatment or incubation prevents this MICA decrease, while up-regulating key cell cycle related molecules such as CDK2, CDK4 and Cyclin D1, as well as apoptosis related molecules making resistant tumor cells now vulnerable to γδ T cell-mediated lysis." (PMID 21935360, 2011). "β-catenin and CYCLIN-D1 are major regulators of tumor cell proliferation and migration." (PMID 21569306, 2011). "Finally, Ccnd1, Gpc3, Mvk, Pparg, Rbl2, and Robo1 exhibited a tumor-specific response, where adverse expression changes were observed for Pparg, which appeared down regulated in transgenic cells (fold change <0.4) and significantly up regulated in tumors." (PMID 21464922, 2011). "Furthermore, relatively higher frequency of cyclin D1 immuno-reactivity was also seen in patients with less differentiated tumours suggesting inverse correlation of cyclin D1 expression with histological differentiation of tumour." (PMID 21537090, 2011). "Finally, CCND1/CDKN2A expressions were measured in formalin fixed paraffin embedded (FFPE) samples of clinical tumor and normal tissues." (PMID 21447152, 2011). "Moreover we tried to evaluate the correlations between galectin-3 and cyclin D1 expression in tumor tissue." (PMID 22024187, 2011). "Similarly, tumor areas ofxenografts showed reduced expression of cyclin D1 in hUCBSC treated tumor sectionswhen compared to the controls." (PMID 21455311, 2011). "In total, 135 tumor samples were examined and classified into three cyclin-D1 expression groups." (PMID 22050898, 2011).
tumor (continued). "Despite complex associations between tumor cells and PanINs, histological and molecular evidence suggests that PanINs can gradually progress to PDAC, bearing genetic traits such as Ras mutations, Cyclin D1 overexpression and loss of p16 expression." (PMID 20569470, 2010). "cyclin D1 staining featured a heterogeneous nuclear staining pattern in tumor cells." (PMID 20704822, 2010). "Besides tumour formation, cyclin D1 can also play a pivotal role in the invasiveness and the metastatic phenotype through the interactions between the malignant cell and the host environment." (PMID 21176227, 2010). "Furthermore, treatment of tumor cell lines with 10μM 4OH-Tam induces the expression of p21Waf1 and p27Kip1, which are known to block the effects of cyclin D1." (PMID 21092078, 2010). "Also supporting this line of evidence is the finding that the tumor suppressor CYLD blocks cyclin D1 expression by inhibiting Bcl-3 signaling." (PMID 20731879, 2010). "The current research shows that down-regulating the expression of cyclin D1 could restrain proliferation of tumor cells." (PMID 20704822, 2010). "Furthermore, MA decreased the expression levels of NF-κB-regulated genes, including genes involved in tumor cell proliferation (Cyclin D1, COX-2 and c-Myc), apoptosis (Survivin, Bcl-2, Bcl-xl, XIAP, IAP-1), invasion (MMP-9 and ICAM-1), and angiogenesis (VEGF)." (PMID 20367887, 2010). "Overexpression of cyclin D1 could alter the process of the cycle and induce excessive proliferation of cell or even tumor." (PMID 20704822, 2010). "Similarly, the level of cyclin D1 protein in tumour stromal cell cultures was higher (L2T, L3T, L5T, L7T and L12T) or lower (L6T, L8T, L9T, L10T and L13T) than in the corresponding normal stromal cell cultures." (PMID 20407446, 2010). "We also present evidence that CCND1 plays a role in tumor cell migration." (PMID 20113529, 2010). "Therefore the downstream target genes, cyclin D1 and c-myc, were induced at a lower level in the tumor cells, compared to that of peritumor cells." (PMID 19402906, 2009). "Tumor cells showed overexpression of cyclin D1 but lacked the loss of heterozygosity of the TSC1 and TSC2 genes." (PMID 19265534, 2009). "Both overexpression of Wnts or their receptor Frizzled proteins, and downregulation of Wnt inhibitors will lead to aberrant activation of Wnt pathway and increase the transcription of Wnt target genes, such as c-myc, cyclin D1 and some MMPs, which are involved in initiation and progression of tumor." (PMID 19586554, 2009). "Accumulation of cyclin D1 together with cyclin-dependent kinases may enhance cell proliferation in tumor cells tissue and may promote cells transition from G0/G1 to S phase." (PMID 19265534, 2009). "In addition, the expression level of cyclin D1 was much higher in peritumor cells compared to that of tumor cells, and c-myc expression showed a similar pattern." (PMID 19402906, 2009). "Considering the wide distribution of cyclin D1 in tumor cells, generation of specific CD4 CTLs, might add therapeutic activity in HLA-DR-expressing cancer cells." (PMID 19707583, 2009). "Furthermore, upregulation of CCND1 gene expression was detected in premalignant lesions adjacent to HNSCC tumours with amplified gene locus." (PMID 19287496, 2009). "CCND1 results were obtained for 27 primary tumours in the CNS PNET cohort." (PMID 19293793, 2009). "However, the significant correlation with CTNNB1 nuclear localisation found particularly in the CNS PNET cohort, strongly suggests that the WNT/β-catenin pathway is increasing CCND1 expression in the tumours with pathway activation in this study." (PMID 19293793, 2009).
tumor (continued). "The significant increase in cyclin D1 expression in therapeutic mastectomy samples supports the idea that secreted factors in the breast stroma can promote increased cell proliferation and thus bring about a tumour-promoting environment." (PMID 19445691, 2009). "Cyclin D1 was examined by IHC in tumor sections using a specific antiserum." (PMID 19473496, 2009). "We found molecular markers in addition to cyclin D1 and characteristic antigens (shared with blood cells from which the tumor may develop) CD5, CD20 and FMC7 with the aim to better delineate the regulatory network regulated differently in MCL." (PMID 18416826, 2008). "Taken together, data elucidating the role of nuclear cyclin D1 in neoplastic transformation support a model wherein disruption of cyclin D1 phosphorylation or SCFFbx4-αBcrystallin activation generate genomic instability, ultimately driving tumor formation." (PMID 18764945, 2008). "We show that exogenous wild-type β−catenin increases CRT, CCND1 promoter activity and tumor cell survival in HCT116 and in HepG2 cells carrying heterozygous β−catenin ΔS45 and Δ25-140, respectively, thus lacking key phosphorylable residues in one of the alleles." (PMID 18382662, 2008). "However, our present study contains mainly high T-stage tumour and the univariate significance of cyclin D1 and FADD implies a link to amplification." (PMID 18268491, 2008). "Similarly, another plant-derived molecule, Guggulsterone, caused cell-cycle arrest in S-phase by the suppression of cyclin D1 and cdc2 and increased CDK inhibitor p21 and p27 expression in a wide variety of human tumour cell types." (PMID 19002174, 2008). "While c-ErbB2 tumours contain more positive markers of the cell cycle than the bitransgenic tumours (phosphorylated Rb and cyclin D1), they also express more negative regulators of the cell cycle (p15 and p27), which likely serves to balance cell cycle progression." (PMID 18700973, 2008). "The activation of IGF1, BCL2 and CCND1 by PTGS2 might be the prolonged legacy of chronic inflammation in early stages of tumor generation." (PMID 17206280, 2007). "Relevance of altered cyclin D1 status was observed, wherein cyclin D1-positive tumours were associated with low preoperative PSA levels, consistent with in vitro reports that cyclin D1 may alter the expression of this tumour marker." (PMID 17375037, 2007). "Further analyses revealed that p21Cip1 may play a role in regulating cyclin D1 dynamics and likely contributes to the observed alterations in tumour characteristics." (PMID 17375037, 2007). "Furthermore, there was a trend for tumours with predominately cytoplasmic cyclin D1 to harbour low proliferative potential as compared to tumours with predominately nuclear cyclin D1." (PMID 17375037, 2007). "The propensity of selected tumour types to induce cyclin D1 accumulation in cancer may therefore be a heterogenous and complex event that culminates in a similar phenotype." (PMID 17375037, 2007). "On the basis of the PSA and proliferation data obtained in our study, it is conceivable that a subset of cyclin D1-positive tumours may exist that have increased proliferation and have low PSA values." (PMID 17375037, 2007). "Interestingly, of the cyclin D1-positive tumours (34/36), disparate cyclin D1 staining was observed in the tumour regions." (PMID 17375037, 2007). "Moreover, tumours with predominantly cytoplasmic cyclin D1 showed the lowest Ki-67 index, whereas nuclear cyclin D1 was associated with higher grade, elevated Ki-67, and increased nuclear p21Cip1." (PMID 17375037, 2007).
tumor (continued). "The progression of this tumor is associated with multiple genetic alterations, including loss of heterozygosity in chromosomes 3p, 5q, 9p, 9q, 13q, 17p, 17q and 18q, and amplification of epidermal growth factor receptor (EGFR), HER-2, c-myc, and cyclin D1." (PMID 17309796, 2007). "For example, it has been shown to repress the transcription of cyclin D1, which is required for cell cycle progression, and increased cyclin D1 expression was shown to be the main reason for the increased tumour formation in tumour prone caveolin-1 knockout mice." (PMID 18949068, 2007). "A series of smaller studies have also reported cyclin D1 induction in tumours compared to normal specimens and at least one of these considered all cyclin D1 localisations (including cytoplasmic and perinuclear) as positive, although correlates according to localisation were not considered." (PMID 17375037, 2007). "In the subset of tumours suited for quantitative PCR analyses, we profiled the mRNA expression of RELA (encoding for RelA/p65) and a number of NF-κB target genes, such as BCL2L1 (Bcl-xL), CCND1 (Cyclin D1), CCND2 (Cyclin D2) and NFKBIA (IκBα)." (PMID 17622249, 2007). "Upregulation of both p21 and cyclin D1 has been reported in several tumours including OSCCs." (PMID 18053169, 2007). "The fourth pattern was represented by those tumours devoid of cyclin D1 (2/36)." (PMID 17375037, 2007). "Interestingly, at least three distinct localisation patterns were observed in the cyclin D1-positive cohort, wherein cytoplasmic localisation was identified in a large fraction, and this pattern was predominant in lower grade tumours." (PMID 17375037, 2007). "Indeed, ER+ tumours were scattered in subgroups 1 to 4 that are characterised by the over-expression of a cluster of genes, which includes CCND1, KRT19, IGF1R, LIV1, ESR1, GATA3, TFF1/pS2, ERBB4, PR and IGFBP4." (PMID 17338809, 2007). "Second, a minority of tumours showed predominately nuclear cyclin D1 (5/36)." (PMID 17375037, 2007). "The mechanism(s) and consequences of this observation will be of significant clinical interest, as these data indicate that cyclin D1 status may suppress tumour marker expression." (PMID 17375037, 2007). "Consistent with a role for cyclin D1 in the proliferation of bone metastatic tumours from prostate, others have reported correlations between metastatic cyclin D1 expression derived from other tumour types." (PMID 17375037, 2007). "Overexpression of cyclin D1 was observed in the tumor nuclei in 27 out of 50 (54%) patients." (PMID 17309796, 2007). "The role of cortactin overexpression on MG tumor development in vivo, either in the absence or presence of co-expression of cyclin D1, was studied in a cohort of 100 multiparous mice that underwent multiple pregnancies/lactations to force transgene expression in the MG." (PMID 16536875, 2006). "The cell cycle regulators, such as ER-α, the ER-α linked cyclin D1, cyclin-dependent kinase 4 (cdk4), and proliferating cell nuclear antigen (PCNA), all followed this pattern of high in tumor tissues, intermediate in tumor-surrounding livers and low in control liver." (PMID 16507464, 2006). "Somatic mutations of this residue have been identified in endometrial and esophageal cancers, thus indicating that disruption of cyclin D1 nuclear export may participate in tumor development and/or progression in this tissue." (PMID 16863592, 2006). "Statistically significant association was observed between tumor proliferative capacity expressed as Ki-67 labeling index and positive cyclin D1 staining (P = 0.045), but not with pRb one." (PMID 16426443, 2006). "The fact that cyclin D1 levels must be suppressed during S phase might also limit tumor formation directly." (PMID 17176475, 2006).